TET2 (tet methylcytosine dioxygenase 2)
Diseases named in the same sentence as TET2 in open-access papers (continued):
Sharing a sentence is not in itself a finding about the gene and the disease.
colon carcinoma (24 papers, 2015 to 2025). "5hmC is increased in metastatic liver tissue relative to the primary colon tumour and expression of TET2 and TET3 is negatively correlated with risk for metastasis in patients with CRC." (PMID 40241172, 2025). "Loss of TET2 in colon tumor cells reduced chemokine expression and the number of TILs, enabling tumors to evade antitumor immunity and resist anti-PD-L1 therapy." (PMID 37488178, 2023). "Nuclear TET2 protects the genome from DNA damage caused by doxorubicin or cisplatin; ultimately, promoting the growth and survival of colon cancer cells and contributing to chemoresistance." (PMID 33256191, 2020). "We performed ChIPseq using HCT116 colon carcinoma cells, identifying ~850 putative target genes associated with metabolism (e.g., Prdx5, Mdh1, Ahcy), transcription (Taf12, Tet2, histones), malignancy (Met, Blcap, Rras, Jag1, Gsk3a) and mitotic stability (Zbtb4)." (PMID 31059499, 2019). "In addition, TET1 and TET2 are downregulated in BRAFV600E-mutated colon cancers." (PMID 35429301, 2022). "We do not have RNA from our metastasis samples, but a publicly available RNAseq dataset for colon cancer with matched liver metastasis confirmed TET2 and TET3 to be the more abundant TET transcripts in colon and liver metastasis." (PMID 40241172, 2025). "An independent data set demonstrated poor metastasis-free survival in patients with high TET2 expression levels and our zebrafish xenograft assays further support a role for TET2 in metastatic transformation in colon cancer." (PMID 40241172, 2025). "Reduced TET2 activity is associated with reduced TH1-type chemokines and tumor-infiltrating lymphocytes (TILs) and the progression of human colon cancer." (PMID 37488178, 2023). "In human ovarian cancer cells and colon cancer cells, TET2 can bind to p300 (a histone acyltransferase) and be acetylated by p300, therefore, the hydroxymethylase activity of TET2 is enhanced." (PMID 33935952, 2021). "We measured the mRNA and protein expression levels of STAT5 and TET2 in CD4+ T cells from colon tumor tissues coupled with corresponding normal colonic tissues." (PMID 30013992, 2018). "Reduction of TET2 nuclear localization may be responsible for the decrease in genomic 5hmC, and TET2 cytoplasmic localization was related with invasive colon cancer subtype." (PMID 32774324, 2020). "Moreover, we also found that the expression of STAT5 and TET2 was increased in CD4+ T cells from colon tumor tissues, and the superfluous STAT5 and TET2 binding to FOXP3-TSDR resulted in DNA hypomethylation." (PMID 30013992, 2018). "Among the TET family (TET1, TET2, and TET3), the suppression of TET1 expression is characteristic of colon cancer." (PMID 39982248, 2025). "Most regulators showed amplification in copy numbers, especially in colon cancer (COAD) and esophageal cancer (ESCA), while the CNV deletions were frequently found on TET2, ALKBH1, and DNMT1." (PMID 37332118, 2023). "Overexpression of BRAFV600E in BRAF wild-type CRC cell lines can significantly repress TET1/TET2 expression, which leads to the hypermethylation of CIMP genes to promote the development of CpG island methylator phenotype colon cancer (CIMP-CC)." (PMID 35429301, 2022). "To confirm that the abnormally increased STAT5 and TET2 bind more strongly to FOXP3-TSDR in CD4+ T cells from colon tumor tissues compared with which from normal tissues, we performed ChIP-qPCR analysis using anti-STAT5 and TET2 antibody." (PMID 30013992, 2018).
colon carcinoma (continued). "In order to validate the interaction between STAT5 and TET2, we performed coimmunoprecipitation using anti-STAT5 in CD4+ T cells from colon tumor tissues." (PMID 30013992, 2018). "Downregulation of TET1 but not TET2 in BRAFV600E tumors was confirmed using TCGA RNA-seq data of 274 colon cancers samples from females." (PMID 31842975, 2019). "In conclusion, high mRNA expressions for LGR5, BMI1, TET1 and TET2 in the CD133 and EpCAM positive CSCs may be a useful criterion for better identification of the cells involved in colon cancer in order to specify therapeutic targets against this type of cancer." (PMID 31057717, 2019). "Although we have potentially eliminated a maintenance role for TET2 in keeping the target promoters free of DNA methylation in colon cancer, this does not preclude the TETs from having an initiating function that marks genes for activation during early development." (PMID 25853800, 2015). "Additionally, TET2 cytoplasmic localization occurs in colon cancer but not in normal tissue." (PMID 32774324, 2020).
angioimmunoblastic T-cell lymphoma (23 papers, 2015 to 2025). A mature T-cell non-Hodgkin lymphoma, characterized by systemic disease and a polymorphous infiltrate involving lymph nodes and extranodal sites. "TET2 mutations have been also identified in mature B-cell (2%) and T-cell (11.9%) lymphomas, in 33% of angioimmunoblastic T-cell lymphomas, in mantle cell lymphomas, and diffuse large B-cell lymphomas." (PMID 34947882, 2021). "The frequency of TET2 repression or loss in T-ALL even exceeds the frequency (30% to 65%) of TET2 loss-of-function mutations observed in angioimmunoblastic T-cell lymphoma in adults (58, –60)." (PMID 34413196, 2021). "Interestingly, in angioimmunoblastic T-cell lymphomas, TET2 mutations are frequently associated with DNA methyltransferase 3A mutations, and IDH2 mutations." (PMID 34947882, 2021). "The TET2 gene, implicated in epigenetic regulation via DNA methylation, is frequently mutated in angioimmunoblastic T-cell lymphoma (AITL) and to a lesser extent in PTCL-NOS." (PMID 39184618, 2024). "For example, RHOA and TET2 mutations are frequently detected in angioimmunoblastic T-cell lymphoma (AITL) and IDH2R172 variant appears to be a unique mutation in AITL." (PMID 33546774, 2021). "Added to this, TET2 is also important in the development of angioimmunoblastic T-cell lymphoma (AITL), being one of the first mutations that appear in this disease." (PMID 33805247, 2021). "Of note, Sample 02 was found to carry another TET2 variant—the p.Tyr1631* stopgain, reported as pathogenic in the COSMIC database and previously identified in angioimmunoblastic T cell lymphoma, CML, and AML at a VAF of 1.4%." (PMID 35033063, 2022). "Both TET2 and RHOA mutations, in particular, are common in angioimmunoblastic T-cell lymphoma (~ 60–70%)." (PMID 33160401, 2020). "Specifically, TET2 has been frequently reported to be mutated in hematological malignancies, including angioimmunoblastic T cell lymphoma (AITL) and peripheral T cell lymphoma, non-otherwise specified (PTCL-NOS)." (PMID 35990681, 2022). "A previous study looking at how mutations in IDH2 and TET2 cells modulates tumorigenesis in angioimmunoblastic T cell lymphoma (AITL) also found a negative correlation between CpG hypermethylation in a differentially methylated region (DMR) of B3GNT3 and its corresponding expression levels." (PMID 38507502, 2024). "Notably, angioimmunoblastic T-cell lymphoma (AITL), which is frequently accompanied by abnormal EBV+ B-cell proliferation, harbor somatic mutations of these epigenetic modulator genes such as TET2 and DNMT3." (PMID 36765793, 2023). "Beginning with nodal PTCLs, up to 60–100% of angioimmunoblastic T-cell lymphoma (AITL) and up to 40% of PTCL not otherwise specified (PTCL-NOS) demonstrate surface markers of follicular helper T (TFH) cells and have common genetic features, such asRHOA,TET2,DNMT3A, andIDH8–11." (PMID 29259783, 2017).
colorectal cancer (21 papers, 2014 to 2026). A primary or metastatic malignant neoplasm that affects the colon or rectum. "In terms of solid tumours, several papers have reported decreased expression of TET2 in cancer tissues and the nuclear loss of TET2 in colorectal cancer tissues." (PMID 37620362, 2023). "The individual with the SRSF2 p.P95L variant is the same patient with the TET2 p.I1873T variant and mast cell leukaemia/colorectal cancer." (PMID 29641532, 2018). "From a pathological perspective, inactivating mutations in TET genes, mainly TET2, frequently occur in various cancers, including haematopoietic malignancies of bone marrow and the lymphatic system and some solid tumours (breast and colorectal cancer)." (PMID 37667220, 2023). "Colorectal Cancer (CRC) progression is a complex and dynamic process closely linked to TET2-mediated DNA demethylation." (PMID 41605908, 2026). "In this study, we explored the dysfunction of TET2 in colorectal cancer and observed that the subcellular localization and DNA demethylation activity of TET2 are critical for CRC progression." (PMID 37620362, 2023). "Nuclear translocation of TET2 was first reported in the B cells; furthermore, our results demonstrated that nuclear translocation of TET2 was also dysregulated in colorectal cancer, probably through the post-translational modification." (PMID 26816554, 2016). "Genome-wide analyses show that promoters marked by 5hmC in normal tissue, and those identified as TET2 targets in colorectal cancer cells, are resistant to methylation gain in cancer." (PMID 25853800, 2015). "The study demonstrated that DNMT1 deletion in colorectal cancer cells led to an upregulation of TET2 expression, re-expression of tumour suppressor proteins (p16ink4A and p15ink4B), CDKN2A promoter demethylation, and associated resistance to DNMTi in DNMT1-deleted cells." (PMID 40011240, 2025). "Finally, moderate inverse correlations were found between TET1 expression and 5-hmdU level (r = − 0.4236, p = 0.035) in persons with polyps, and between TET2 expression and 5-cadC level (r = − 0.5324, p = 0.023) in colorectal cancer patients." (PMID 30029654, 2018). "Our results indicate a new mechanism of TET2 dysregulation in colorectal cancer." (PMID 26816554, 2016). "TET2 represents a critical regulator for normal and malignant hematopoiesis, and its expression has recently been shown to represent a prognostic factor for colorectal carcinoma recurrence and outcome." (PMID 27129173, 2016). "However, the role of TET2 in solid cancers, including colorectal cancer (CRC), is unclear." (PMID 37620362, 2023). "In a follow up study, the authors showed a link between TET2 and resistance to DNMTi in DNMT1 depleted colorectal cancer cells." (PMID 40011240, 2025). "Thus, TET2 could also be a tumor suppressor in colorectal cancer, and the tumor suppressor function of both TET1 and TET2 was impaired in colorectal cancer through different mechanism." (PMID 26816554, 2016).
glioblastoma (21 papers, 2012 to 2025). The most malignant astrocytic tumor (WHO grade IV). "TET2 loss is associated with glioblastoma (GBM) stem cells and correlates with low survival in GBM patients." (PMID 37934565, 2023). "We show that TET2 loss associates with glioblastoma (GBM) stem cells and correlates with poor survival of GBM patients." (PMID 35136034, 2022). "TET2 deletion enhances stemness in glioblastoma cells and induces a more aggressive tumor phenotype." (PMID 40599235, 2025). "The importance of miR-10b-5p-mediated suppression of Ten-eleven translocation 2 (TET2) in immune evasion induced by PD-L1 and suggests their potential as targets for immunotherapy in glioblastoma (GBM) are demonstrated." (PMID 38462628, 2024). "For instance, ALKBH1 and TET2 mutations are associated with myeloid and lymphoblastic leukemias, while TET1 is highly expressed in glioblastoma." (PMID 36360287, 2022). "Significant heterogeneity in the expression of TET2 protein in glioblastoma was also noted by Briand." (PMID 35494033, 2022). "MiR-101-3p promotes apoptosis of oral cancer cells by targeting BICC1, induces dysfunction of vascular endothelial cell by targeting tet methylcytosine dioxygenase 2, suppresses proliferation and metastasis of glioblastoma cells via targeting TRIM44." (PMID 34977016, 2021). "Ectopic overexpression of TET2 regulated neural differentiation in glioblastoma cell lines and impaired tumor growth." (PMID 29899831, 2018). "To identify alternative molecular mechanisms involved in TET2 downregulation in glioblastoma we considered the possible role of epigenetic factors by analyzing the TET2 promoter and intergenic levels of 5 mC, 5 hmC and H4K16ac in control and tumoral samples." (PMID 29899831, 2018). "We also detected changes in neuron-specific microRNA miR-124 and oligodendrocyte-specific microRNA miR-338 expression when TET2 activity is restored in LN229 glioblastoma cell line." (PMID 29899831, 2018). "Here we report that TET2 shows frequent epigenetic alterations in human glioblastoma including DNA hypermethylation and hypo-hydroxymethylation, as well as loss of histone acetylation." (PMID 29899831, 2018). "To study the effect of TET2 expression in glioblastoma in vivo we tested the ability of TET2-transfected LN229 cells to form tumors in nude mice as compared with control cells transfected with an empty vector." (PMID 29899831, 2018). "In the same vein, TET2 protein expression was stronger in the control brain samples than in primary glioblastoma samples." (PMID 29899831, 2018). "TET2 expression was lower in primary glioblastomas and glioblastoma cell lines than in control samples (Wilcoxon rank sum test, p-value < 0.05 for cell lines)." (PMID 29899831, 2018). "Similarly, miRNAs involved in TET2 regulation to mediate glioblastoma development also include miR‐19a‐5p." (PMID 40599235, 2025). "Notably, it has been reported that miR-19a-5p can negatively regulate the expression of TET2 in glioblastoma." (PMID 34429758, 2021). "Interestingly, miR-19a-5p was shown to be sponged by the lncRNA AC016405.3 which repressed the glioblastoma cells by reestablishing the expression of TET2." (PMID 33805247, 2021). "MiR-19a-5p targets TET2 in glioblastoma inducing proliferation and metastasis." (PMID 33805247, 2021). "Additionally, we revealed that the overexpression of the DNA demethylase Ten-eleven translocation 2 (TET2) in IDH1-plasmid transfected glioblastoma multiforme (GBM) cells restored G0S2 expression." (PMID 30388142, 2018). "Our results suggest that epigenetic dysregulation of TET2 plays a role in human glioblastoma." (PMID 29899831, 2018). "In support of this, reduction in TET2 enzyme levels by promoter methylation has recently been reported in low grade diffuse gliomas lacking IDH1/2 mutations, and loss of the TET2 locus (4q24) has been reported in approximately 2% of glioblastomas." (PMID 22829908, 2012).
glioblastoma (continued). "IDH1/2 mutations are frequent in low-grade gliomas (LGG) and glioblastomas (GBM), which produce oncometabolite 2-HG and inhibit TET2 activity." (PMID 37550284, 2023). "In addition, HIF-1α deletion in glioblastoma cells was shown to increase TET2 transcription and translation levels and further promote ascorba-induced and TET2-dependent 5hmC, suggesting that HIF-1α is involved in regulating TET2 expression and 5hmC levels in malignant cells." (PMID 33109235, 2020). "Interestingly, although TET2 is not frequently mutated in glioblastoma, it has been found to be frequently downregulated." (PMID 29899831, 2018). "To determine the possible role of TET2 epigenetic dysregulation in gene expression, we first compared the mRNA expression level of TET2 in 14 non-tumorigenic brain samples, 7 samples obtained from patients with glioblastoma multiforme and 4 glioblastoma cell lines." (PMID 29899831, 2018). "To address this issue, we transfected TET2 in the glioblastoma cell line LN229, which exhibits hypo-hydroxymethylation as well as downregulation of TET2 mRNA." (PMID 29899831, 2018). "We determined the DNA methylation and hydroxymethylation status of 21 CpG positions within TET2 promoter DNA regions and the gene body in 9 samples obtained from patients with glioblastoma and 5 from non-tumorigenic brain samples." (PMID 29899831, 2018).